REN (renin)
Diseases named in the same sentence as REN in open-access papers (continued):
Sharing a sentence is not in itself a finding about the gene and the disease.
glioblastoma (continued). "There is an emerging role for the renin–angiotensin system in tumour progression, which may play a role in glioblastoma and facilitate a pro-tumour microenvironment." (PMID 38607073, 2024). "Interestingly, AGT was higher in expression in both glioblastomas and low-grade gliomas, while REN expression was comparatively lower when compared to the majority of the other tumour types." (PMID 38607073, 2024). "Conversely, AGT and REN had lower expressions in glioblastomas compared to low-grade gliomas." (PMID 38607073, 2024). "Inhibition of renin in glioblastoma cells may be a potential approach to control glioblastoma cell proliferation and survival, and glioblastoma progression in combination therapy." (PMID 14997208, 2004). "These issues need to be resolved, but renin inhibition, in combination therapy with other drugs, may be a potential approach to control glioblastoma progression." (PMID 14997208, 2004). "However, the addition of selective synthetic renin inhibitors to glioblastoma cells decreased DNA synthesis and viable tumour cell number, and induced apoptosis." (PMID 14997208, 2004). "Thus, human glioblastoma cells produce renin and AGT and secrete AGT." (PMID 14997208, 2004). "Progression-free survival (PFS) and overall survival (OS) were compared across TCGA glioblastoma cases, stratified from high and low expression of ATP6AP2, AGTR1, AGTR2, ACE, AGT, and REN genes." (PMID 38607073, 2024). "In cases of glioblastoma within the TCGA, ATP6AP2, AGTR1, ACE, and AGT had consistent expressions across samples, while AGTR2 and REN were lowly expressed." (PMID 38607073, 2024). "The majority of genes (ATP6AP2, AGTR1, ACE, and AGT) were consistently expressed in glioblastoma cases, with the exception of AGTR2 and REN." (PMID 38607073, 2024). "To investigate the expression of the renin–angiotensin system (RAS) in cancer stem cells (CSCs), we have previously characterized in glioblastoma multiforme (GBM)." (PMID 27730123, 2016). "Second, we have shown that renin has a direct role in glioblastoma cell proliferation and/or survival and that inhibitors of the enzyme induce a fast and important loss of proliferation and survival of glioblastoma cells, independent of the action of angiotensin peptides on their cognate receptors." (PMID 14997208, 2004). "To address the functions of the RAS in human glioblastoma, we first evaluated the effect of inhibiting renin and ACE in glioblastoma cells." (PMID 14997208, 2004). "Renin and angiotensinogen (AGT) mRNAs and proteins were found by in situ hybridisation and immunohistochemistry in glioblastoma cells." (PMID 14997208, 2004). "We showed that AGT, TDP renin substrate and Ang peptides did not play any role in glioblastoma cell growth, apoptosis and/or DNA synthesis." (PMID 14997208, 2004). "Therefore, in the present study, we report the expression and functions of renin, AGT and angiotensin peptides in human glioblastoma tumours and human glioblastoma cells in culture." (PMID 14997208, 2004). "We had previously shown using an IRMA immunoassay that renin protein can be measured in cell extracts of human glioblastoma cells, but not in the culture supernatants." (PMID 14997208, 2004). "Overall, REN was lowly expressed in gliomas within the TCGA compared with the majority of other cancers, suggesting the source of prorenin for the activity of RAS in glioblastoma may be external to the tumour." (PMID 38607073, 2024). "The role of renin in cancer has not been well studied, although it has been found to be upregulated in various cancer types, and attenuation of renin has been shown to reduce cell growth and induce apoptosis in glioblastoma." (PMID 33147716, 2020). "We have previously shown that human glioblastoma cells do not secrete renin." (PMID 14997208, 2004). "The presence of FCS did not modify glioblastoma cell response to the renin inhibitors." (PMID 14997208, 2004).
glioblastoma (continued). "Together, these results suggest that human glioblastoma cells have the potential to produce AGT, prorenin/renin and Ang I, but not to convert Ang I into Ang II." (PMID 14997208, 2004). "Angiotensinogen, des(Ang I)AGT, tetradecapaptide renin substrate (AGT1–14), Ang I, Ang II or Ang III, added to glioblastoma cells in culture, did not modulate their proliferation, survival or death." (PMID 14997208, 2004). "The majority of glioblastoma cases expressed ATP6AP2, AGTR1, ACE, and AGT but not AGTR2 and REN." (PMID 38607073, 2024).
Hypoalbuminemia (13 papers, 2013 to 2025). The concentration of albumin in the blood circulation is below the lower limit of normal. "Hypoalbuminemia is associated with decreased intravascular volume secondary to increased fluid third spacing, which results in activation of the renin-angiotensin system and causes increased renal vasoconstriction and hypoperfusion, exacerbating the hemodynamic state leading to HRS." (PMID 38752039, 2024). "In patients with lower sK, nephrotic range proteinuria, and hypoalbuminemia were more prevalent but the use of RAS (renin-angiotensin system) inhibitors was less frequent." (PMID 23843989, 2013). "The reduced serum levels of Zn, Cu and Se in UNX rats might be due to the decreased renal tubular reabsorption, renin–angiotensin system activation and hypoalbuminaemia." (PMID 36420617, 2023). "Thirdly, low sACR may suggest neuroendocrine activation, particularly the persistent activation of the renin-angiotensin-aldosterone system and the sympathetic nervous system, which could lead to increased protein catabolism, hypoalbuminemia and elevated creatinine levels." (PMID 39027002, 2024).
melanoma (13 papers, 2014 to 2025). A malignant, usually aggressive tumor composed of atypical, neoplastic melanocytes. "In the FinnGen dataset, genetic liability to the use of agents acting on the renin–angiotensin system (C09) was suggestively associated with an increased risk of malignant melanoma." (PMID 41153759, 2025). "Previous studies have demonstrated an association of the use of ACE inhibitors and angiotensin II receptor 1 blockers with reduced risk of development of skin SCC, and β-blockers administration which reduce renin levels, is associated with improved survival of patients with malignant melanoma." (PMID 28634582, 2017). "Additional research is needed to determine the precise regulatory impact of paracrine renin–angiotensin system signaling on these CSCs, which are proposed drivers of melanoma and treatment resistance." (PMID 39941158, 2025). "The observation that AT2R antagonists potentiate the effects of BRAF and MEK inhibitors underscores the potential benefits of combining renin–angiotensin system inhibitors with targeted therapies for melanoma." (PMID 39941158, 2025). "Renin–angiotensin system dysregulation is common in many cancer types, including melanoma, with experimental models demonstrating that renin–angiotensin system inhibition reduces tumor growth, angiogenesis, and metastasis." (PMID 39941158, 2025). "CSCs reside within the tumor microenvironment (TME) regulated by the immune system, and the paracrine renin–angiotensin system, which is expressed in many cancer types, including melanoma." (PMID 39941158, 2025). "Together, these findings suggest a potential role for renin–angiotensin system regulation in the treatment of melanoma." (PMID 39941158, 2025). "This review highlights the complex interplay between CSCs, the TME, the paracrine renin–angiotensin system, and dysregulated signaling pathways, in melanoma." (PMID 39941158, 2025). "Further, SOX2+/OCT4+ phenotypic CSCs in metastatic melanoma to the brain and the head and neck lymph nodes express components of the renin–angiotensin system, a pathway well described in brain tissue." (PMID 39941158, 2025). "This article explores the interplay between CSCs and the paracrine renin–angiotensin system in the melanoma TME, and their interaction with the dysregulated Ras/RAF/MAPK/ERK and PI3K/AKT/mTOR signaling pathways, highlighting their implications on current therapeutic approaches." (PMID 39941158, 2025). "Further exploration of the effects of renin–angiotensin system inhibition on melanoma TME may yield valuable insights into novel treatment strategies." (PMID 39941158, 2025). "Furthermore, 137 pathways were enriched by candidate characteristic genes, including the PI3K-Akt signaling pathway, prostate cancer, terpenoid backbone biosynthesis, renin secretion, and melanoma, etc." (PMID 41305715, 2025). "The paracrine renin–angiotensin system within the melanoma TME may play an important role in maintaining melanoma CSCs through its interaction with the Ras/RAF/MAPK/ERK and PI3K/AKT/mTOR pathways." (PMID 39941158, 2025). "Furthermore, renin–angiotensin system inhibitors potentiate the effect of BRAF and MEK inhibitors in BRAFV600-mutated melanoma cells." (PMID 39941158, 2025). "Combined treatment involving renin–angiotensin system inhibitors, targeted therapy, and/or immunotherapy, and possibly mRNA vaccines may offer more a durable treatment for advanced melanoma." (PMID 39941158, 2025). "In this article, we explore the mechanisms of resistance to targeted inhibitors, focusing on the interaction between the paracrine renin–angiotensin system within the melanoma TME and the Ras/RAF/MAPK/ERK and PI3K/AKT/mTOR pathways, as well as the role of CSCs regulated by these pathways." (PMID 39941158, 2025). "In melanoma, the renin-angiotensin system has both tumor suppressor and oncogenic effects." (PMID 34066301, 2021).
melanoma (continued). "Compared with non-use, we observed a slightly increased melanoma risk in users of diuretics (RR 1.08, CI 1.01–1.15), calcium-channel blockers (RR 1.10, CI 1.04–1.18) and drugs affecting the renin-angiotensin system (RR 1.10, CI 1.04–1.16), but not for beta blockers (RR 0.97, CI 0.92–1.03)." (PMID 36413027, 2023). "Given the established role of Wnt signaling in the regulation of ESCs and the pathogenesis of melanoma, further investigation is warranted to elucidate how renin–angiotensin system modulation affects Wnt pathway activity and CSC properties in the melanoma TME." (PMID 39941158, 2025). "This narrative review discusses the role of CSCs and the paracrine renin–angiotensin system in the melanoma TME, and its implications on the current treatment of advanced melanoma with targeted therapy and immune checkpoint blockers." (PMID 39941158, 2025). "The convergence of the renin–angiotensin system onto the Ras/RAF/MAPK/ERK and PI3K/AKT/mTOR pathways in melanoma presents exciting research avenues for therapeutic interventions." (PMID 39941158, 2025). "The presence of these immunosuppressive cells within the melanoma TME, and their interaction with the paracrine renin–angiotensin system, highlight possible therapeutic avenues." (PMID 39941158, 2025). "Interactions between melanoma CSCs and the TME, influenced by the paracrine renin–angiotensin system, is suggested by the expression of components of the renin–angiotensin system by phenotypic CSCs in metastatic melanoma." (PMID 39941158, 2025). "Targeting the paracrine renin–angiotensin system may disrupt signaling critical for CSC maintenance, thereby halting melanoma progression, treatment resistance, and recurrence." (PMID 39941158, 2025). "Our data obtained in neuronal, melanoma, hepatoma and epithelial cells in the absence of stimulation with the ligand (pro)renin indicate that the (P)RR exerts additional constitutive, cell type-independent pro-proliferative/pro-survival effects." (PMID 24424509, 2014). "The dysregulated paracrine renin–angiotensin system, especially through the binding of ATII to AT1R, may enhance melanoma CSC properties by activating the Ras/RAF/MAPK/ERK and PI3K/AKT/mTOR pathways, ultimately leading to the increased expression of CSC markers and self-renewal capacity." (PMID 39941158, 2025). "Renin–angiotensin system inhibition may affect not only AT1R and AT2R signaling, but also its interactions with the overactive Ras/RAF/MAPK/ERK and PI3K/AKT/mTOR pathways in melanoma." (PMID 39941158, 2025).
nephrotic syndrome (13 papers, 2007 to 2025). A collection of symptoms that include severe edema, proteinuria, and hypoalbuminemia; it is indicative of renal dysfunction. "Diabetic kidney disease (DKD) can induce secondary nephrotic syndrome, which is often challenging to manage with conventional treatments such as renin-angiotensin system inhibitors and diuretics." (PMID 40276452, 2025). "Studies have shown that patients with nephrotic syndrome can have high, low, or even normal renin levels, mainly because edema is a dynamic process." (PMID 38540182, 2024). "Sodium retention and edema are common features of nephrotic syndrome that are classically attributed to hypovolemia and activation of the renin–angiotensin–aldosterone system." (PMID 17554565, 2007). "A renin–angiotensin system inhibitor was prescribed for nephrotic syndrome." (PMID 39072328, 2024). "In this study we analysed whether PLA2R-Ab levels might predict development of nephrotic syndrome and the clinical outcome in 33 patients with biopsy-proven primary MN and non-nephrotic proteinuria under treatment with blockers of the renin-angiotensin system." (PMID 25313791, 2014). "It is, however, unclear whether non-nephrotic proteinuria at the time of diagnosis is also associated with good prognosis since a reasonable number of these patients develop nephrotic syndrome despite blockade of the renin-angiotensin system." (PMID 25313791, 2014). "The aim of our study was to describe patterning of Cxs and renin in JGA of developing and postnatal healthy human kidneys and nephrotic syndrome of the Finnish type (CNF) which gradually leads to CKD." (PMID 33172216, 2020). "Renin-angiotensin system inhibitors are important renoprotective agents for nephrotic syndrome; however, caution should be exercised in cases of AKI complications, especially when patients with nephrotic syndrome are treated with two different RAS inhibitors." (PMID 36407214, 2022). "Twenty-nine patients with nephrotic syndrome and six patients without urinary protein or acid–base disturbances provided blood and urine samples for analysis that included routine biochemical and arterial blood gas tests, plasma renin activity, and aldosterone." (PMID 28289910, 2017).
non-alcoholic fatty liver disease (13 papers, 2016 to 2025). "The mineralocorticoid receptor (MR) and renin-angiotensin-aldosterone system (RAAS) are implicated in non-alcoholic liver fatty disease (NALFD)." (PMID 33391254, 2020). "The renin-angiotensin system (RAS) is involved in the pathogenesis of non-alcoholic fatty liver disease (NAFLD) and represents a potential therapeutic target for NAFLD." (PMID 32322207, 2020). "Tekatas DD, Bahcecioglu IH, Ispiroglu M, Sahin A, Ilhan N, Yalniz M, Demirel U. Role of Renin–Angiotensin-converting Enzyme Level and ACE Gene Polymorphism in Patients with Nonalcoholic Fatty Liver Disease." (PMID 29201746, 2016). "In mice with non‐alcoholic fatty liver disease (NAFLD), the classical renin‐angiotensin (RAS) axis was activated, leading to oxidative stress, inflammation, and histopathological changes in the liver." (PMID 40046578, 2025).
obstructive sleep apnea (13 papers, 2008 to 2025). "Obstructive sleep apnea is highly correlated with increased sympathetic tone and renin-angiotensin system mainly by hypoxia/hypercapnia." (PMID 35992203, 2022). "Hyperleptinemia and obstructive sleep apnea, frequently found in obese person, can activate the sympathetic nervous system which can in turn stimulate renin release and activate systemic RAS system." (PMID 32252748, 2020). "Obstructive sleep apnea (OSA) may contribute to kidney injury by activation of the renin–angiotensin system (RAS), which is reduced by continuous positive airway pressure (CPAP) therapy." (PMID 32207249, 2020). "Patient 2 was diagnosed with idiopathic hyperaldosteronism combined with obstructive sleep apnea syndrome, which could increase renin resulting in a negative ARR, and finally got a better treatment effect with PA-specific spironolactone, as well as continuous positive airway pressure." (PMID 37335717, 2023).
prostate carcinoma (13 papers, 2011 to 2025). A carcinoma that arises from epithelial cells of the prostate gland. "The protective effect of ACEIs in patients with prostate cancer has been suggested to possibly be linked to increased levels of renin and Ag-I, with subsequent downstream effects on bradykinin and prostaglandins, whilst potentially reducing Ag-II." (PMID 39861167, 2025). "There was a negative association between the use of agents acting on the renin-angiotensin system and prostate cancer risk." (PMID 38487860, 2024). "Another study found that individuals with the ACE genotype tend to smoke and that smoking increases renin activity, which promotes angiotensin II production, increasing the risk of prostate cancer." (PMID 38487860, 2024). "Our study provides robust evidence that the use of drugs acting on the renin-angiotensin system can reduce prostate cancer risk." (PMID 38487860, 2024). "Our study provides robust evidence that the use of drugs acting on the renin-angiotensin system can reduce the risk of prostate cancer." (PMID 38487860, 2024). "In general, the combined results of large cross-sectional studies and MR analysis identified robust evidence that using agents acting on the renin-angiotensin system can reduce the risk of prostate cancer." (PMID 38487860, 2024). "Comprehensive MR analysis provided evidence for a causal effect of agents acting on the renin-angiotensin system on a decreased risk of prostate cancer." (PMID 38487860, 2024). "Combining the cross-sectional study results in NHANES and the MR analysis, we observed an association between agents acting on the renin-angiotensin system use and prostate cancer." (PMID 38487860, 2024). "A nonlinear relationship of ‘decrease-to-increase-to-decrease’ was observed between the duration of use of agents acting on the renin-angiotensin system and prostate cancer risk." (PMID 38487860, 2024). "We found that the use of agents acting on the renin-angiotensin system was associated with reduced risk of prostate cancer (odds ratio (OR) = 0.42; 95% confidence interval (CI) = 0.27–0.63, P < 0.001), and there was a nonlinear association of ‘decrease-to-increase-to-decrease’ (P < 0.0001)." (PMID 38487860, 2024). "We also found a negative causal effect of genetic predisposition towards agents acting on the renin-angiotensin system (OR = 0.94; 95% CI = 0.91–0.97, P = 0.0007) in prostate cancer, whereas vasodilators used in cardiac diseases were detrimental (OR = 1.25; 95% CI = 1.13–1.38, P = 2.48E–05)." (PMID 38487860, 2024). "Survey-weighted RCS analysis revealed an s-shaped nonlinear relationship between the use of agents acting on the renin-angiotensin system and prostate cancer." (PMID 38487860, 2024). "Specifically, survey-weighted multivariate logistic regression showed that the use of agents that act on the renin-angiotensin system reduced the chances of prostate cancer (OR = 0.42; 95% CI = 0.27–0.63, P < 0.001)." (PMID 38487860, 2024). "Regarding the renin-angiotensin system, previous literature has shown that angiotensin II induces OS in prostate cancer and promotes inflammation." (PMID 36268283, 2022). "There are 3 of them confirmed they are related to SLE by literatures, including calcium signaling pathway, renin-angiotensin system and prostate cancer." (PMID 29312536, 2017). "From a large genome-wide association study in patients with prostate cancer it was previously reported that SNPs tagging AGT, part of the renin-angiotensin system (RAS), correlated with patient-reported late hematuria, identifying a potential targetable pathway to prevent RT-induced bladder injury." (PMID 36400304, 2023). "A functional Renin-Angiotensin system has beendemonstrated in prostate cancer." (PMID 21479216, 2011).